CD4 (CD4 molecule)
Diseases named in the same sentence as CD4 in open-access papers (continued):
Sharing a sentence is not in itself a finding about the gene and the disease.
malaria (continued). "Recently, it has been shown that, there is an association between the frequency of RTS,S/AS01E induced (circumsporozoite protein) CSP-specific CD4+ T cells and protection from clinical malaria, most strongly seen for IFNc-IL2-TNF + CD4+ T cells." (PMID 23496910, 2013). "It is noteworthy that the same sets of overlapping peptides used in our ELISpot assay were able to detect more malaria-specific IFN-γ-secreting CD8+ T cells than CD4+ T cells from PBMCs of human volunteers vaccinated with AdPfCA." (PMID 24205224, 2013). "In malaria individuals, a higher prevalence of activated CD4+ than CD8+ T cells was observed, in both ex-vivo and in 96 h culture in presence of PvMSP-119 and PSS1 antigen." (PMID 24041406, 2013). "In malaria individuals, CD4+ T cells were more activated (16.1 ± 12.2%) than CD8+ T cells (3.2 ± 3.3%)." (PMID 24041406, 2013). "On the other hand, there are examples where they can drive pathogenesis and, despite extensive efforts, in most instances, such as in malaria, it is still unclear under which circumstances CD4 T cells mediate either protective immunity or immunopathology." (PMID 23383106, 2013). "In a time when HAART is being rapidly scaled-up globally, there is a need to determine the impact of APFP on the profile of immunological parameters, particularly on the profile of CD4+ T cells counts in regions where both malaria and HIV are highly prevalent." (PMID 23710648, 2013). "With regard to malaria, PfCSP plus polyI:C produced specific robust and functional antibodies, as well as improved CD4+ T cell responses in comparison to RTS,S/AS01B vaccine in primates." (PMID 23710439, 2013). "Blood specimens were examined for complete blood count, CD4 count and blood film for malaria hemoparasite; whereas stool specimens were checked for ova of intestinal parasites." (PMID 23977253, 2013). "CD4+ T lymphocytes decline temporarily during clinical malaria episodes in both HIV-infected and uninfected patients." (PMID 22853699, 2012). "We also show that IFNγ-IL2+TNF−, IFNγ-IL2+TNF+, and IFNγ-IL2-TNF+ CD4+ T cells were induced by natural exposure to malaria in the control vaccinees." (PMID 23300801, 2012). "The concomitant production of IL-2 and expression of high affinity IL-2R by activated CD4+ T cells during acute infection implicates this cytokine as a participant in the immune response to P. chabaudi malaria." (PMID 22272258, 2012). "By contrast, CD4+ T-cell responses to one CIDRα domain were observed in both malaria-exposed and unexposed individuals but only the response in malaria-exposed individuals was MHC class II restricted." (PMID 22272280, 2012). "Antigen-specific, cytokine producing CD4+ T-cells were detected in 58% (n = 24) and 46% (n = 20) of children 4 weeks and 16 weeks after the acute malaria attack, respectively." (PMID 22272280, 2012). "During acute bouts of clinical malaria, plasma HIV-1 RNA levels rise, and CD4 cells decline by approximately 40 cells/μL/year with each malaria episode compared to the rate of decline in individuals without clinical malaria episodes." (PMID 22745697, 2012). "Protective immunity against blood-stage Plasmodium requires malaria-specific CD4+ T cells to rapidly and effectively control parasitaemia and clear the infection." (PMID 22873687, 2012). "Others have demonstrated that overt clinical bouts of malaria are associated with increased levels of HIV-1 RNA and of CD4 cell decline." (PMID 22853699, 2012). "We observed a general trend toward increased CD4 memory T-cell activation in the Day 56 malaria exposed donor PBMCs compared to naïve control PBMCs after 72 and 96 hours." (PMID 22745697, 2012). "Although antigen-specific antibodies are considered the main effector mechanism in immunity to malaria, the induction of efficient and long-lasting antibody responses requires CD4+ T-cell help." (PMID 22272280, 2012).
malaria (continued). "Animal models of malaria have shown that fully functional memory CD4+ T-cells are maintained for prolonged periods of time." (PMID 22745697, 2012). "Some have proposed that memory responses to malaria are very short lived and that malaria specific CD4+ T-cells are deleted, resulting in very little memory against future infection." (PMID 22745697, 2012). "This work reinforces the idea that the CD4+ T cell response to P. chabaudi malaria develops in two distinct phases wherein JES6-1 treatment impairs the expansion of Treg cell population at the early phase and enhances the Th1 cell response at the late phase." (PMID 22272258, 2012). "Among CD3+ T cells, the median percentage of CD4+CD25hi T cells in the uninfected malaria-exposed controls was significantly higher (3%, N = 17) than that of the unexposed controls (2%, N = 21, MD = 0.9, 95%CI = 0.1–1.7, P = 0.02)." (PMID 23049909, 2012). "Hazard Ratios (HR) and 95% Confidence intervals from Cox regression models for the effect of CD4+ cellular responses to CSP on clinical malaria episodes." (PMID 23300801, 2012). "We have recently proposed that the splenic CD4+ T cell response to blood stages of P. chabaudi malaria develops in two consecutive phases where conventional CD4+ T cells are the main protagonists." (PMID 22272258, 2012). "We expressed recombinant DBLα-tags from parasites isolated from clinical cases of malaria and determined CD4+ T-cell responses in those children who provided the clinical parasite isolate at the time of acute disease and during convalescence." (PMID 22272280, 2012). "Although the contribution of CD4+ T cells to blood-stage malaria immunity has been extensively studied, the development and maintenance of malaria-specific memory CD4+ T cells is not well understood." (PMID 21347351, 2011). "Based on the B cell numbers per spleen, we concluded that CD1d-restricted and I-Ab-restricted CD4+ T cells contribute to the expansion of the spleen B cell population during early P. chabaudi malaria." (PMID 21814579, 2011). "The QC panel samples for epidemic bacteria, malaria and TB microscopy, CD4 counts, HIV ELISA and Western Blot are received from the National Institute of Public Health (NIPH) in South Africa every quarter." (PMID 21702948, 2011). "The pivotal role of spleen CD4+ T cells in the development of both malaria pathogenesis and protective immunity makes necessary a profound comprehension of the mechanisms involved in their activation and regulation during Plasmodium infection." (PMID 21814579, 2011). "The present work adds basic information to the malaria literature and opens the perspective of future studies to unravel the molecular mechanisms involved in the early phase of the spleen CD4+ T cell response to Plasmodium infection." (PMID 21814579, 2011). "Here, we analysed malaria-specific CD4+ T cell responses of individuals living in an area of low malaria transmission in northern Thailand, who had had a documented clinical attack of P. falciparum and/or P. vivax in the past 6 years." (PMID 21347351, 2011). "The immunopathogy of malaria is dependent on both the Plasmodium species involved and the regulatory mechanisms dependent on CD4 T cells." (PMID 21917128, 2011). "In line with previous studies, we observed that CD4+ T cells from both malaria-naïve and malaria-exposed individuals proliferated extensively when co-cultured with PfSE." (PMID 21347351, 2011). "MSP1-specific CD4 T cell responses and antibody can confer protective immunity in experimental models of malaria." (PMID 22053177, 2011). "Hence, while neither CD4+ TNFα+ cells nor anti-CS antibodies alone accounted for all of the effect of vaccination with RTS,S/AS01E on clinical malaria risk, the combination of CD4+ TNFα+ T cells and anti-CS antibodies together could account for all of the statistical effect of vaccination." (PMID 21998698, 2011).
malaria (continued). "In an extension of this study, we have now examined both the short-term (12 months of the study) and long-term (history of infection in the past 6 years) stability of the CD4+ T cell memory responses to malaria antigens." (PMID 21347351, 2011). "The pivotal role of CD4+ T cells in the development of both malaria pathogenesis and protective immunity makes them putative targets for new strategies to improve the outcome of the disease." (PMID 21814579, 2011). "Naturally acquired protective immunity against blood stage malaria involves both antibodies and CD4+ T cells." (PMID 21347351, 2011). "In rodent malaria models, there is strong evidence for the role of CD4+ T cells, interferon-gamma (IFN-γ) and nitric oxide contributing to the control of blood-stage parasitaemia, including those cells against the AMA1 antigen." (PMID 21698193, 2011). "We believe that clarifying these issues will help to develop new strategies to ameliorate the outcome of malaria by minimising the undesirable effects of the early CD4+ T cell response to Plasmodium infection." (PMID 21814579, 2011). "By contrast, naïve mice presented CD4+CD25+ percentages (2.0%) were three fold lower than those detected in malaria-infected mice." (PMID 21464982, 2011). "Correlations of P. falciparum antigen specific CD4+ T-cell responses with resistance to malaria in humans have been reported." (PMID 21303495, 2011). "Both malaria-elicited Treg subsets appeared to be derived from conventional CD4+CD25−Foxp3− T cells." (PMID 20442856, 2010). "Studies in malaria patients indicate that higher frequencies of peripheral blood CD4+ Foxp3+ CD25+ regulatory T (Treg) cells correlate with increased blood parasitemia." (PMID 21170302, 2010). "Here we have used CD4+ T cells from a transgenic mouse carrying a T cell receptor specific for a malaria protein, Merozoite Surface Protein-1, to investigate memory in a Plasmodium chabaudi infection." (PMID 21124875, 2010). "Protective cellular immune responses against malaria can be initiated by antigen-presenting cells (e.g. dendritic cells) that ultimately activate specific CD4+ and CD8+ T cells." (PMID 20224778, 2010). "In the acute uncomplicated malaria, it has been demonstrated that peripheral blood CD4+ T cells producing both IFN-γ and IL-10 were significantly increased during drug-induced clearance of parasitaemia." (PMID 20856680, 2010). "Overall, vaccination induced an increase in the frequency of malaria specific CD4+ and CD8+ lymphocytes in 16 out of 22 volunteers (73%)." (PMID 19798415, 2009). "These are matching the potent IgG response induced by RTS,S, and improving upon either the malaria-specific CD8+ or the CD4+ T cell responses." (PMID 20042088, 2009). "Controls with uncomplicated malaria were more likely than asymptomatic controls to have a CD4 count <350/μL (OR 7.67, 95% CI 1.78–33.01, p = 0.001)." (PMID 19402961, 2009). "In this study we investigated the role of commonly accepted factors for Foxp3 induction, TCR stimulation and cytokines such as IL-2, TGFβ and IL-10, in the generation of human CD4+CD25+Foxp3+ T cells by the malaria parasite Plasmodium falciparum." (PMID 19680449, 2009). "Quantifying changes in antigen-specific responses among CD4+ and CD8+ T cells longitudinally will help to determine if the SIV infection does indeed result in a loss of antigen recall to the malaria parasite." (PMID 19774084, 2009). "CD4 T cells recognizing HGXPRT confer protection in a murine malaria model and the current study now demonstrates robust T cell proliferation to Plasmodium HGXPRT protein and peptides during human malaria infection." (PMID 19500406, 2009). "The numbers of naïve CD4+ T cells fluctuated in response to the parasite blood stage during relapses (malaria-only group)." (PMID 19774084, 2009). "Eighty-three percent of case-patients had a CD4 count <350/μL, compared with 79% of controls with uncomplicated malaria (p = 0.76) and 8% of asymptomatic controls (p<0.0001)." (PMID 19402961, 2009).
malaria (continued). "The generation of CCR5+ memory and central memory CD4+ T cells in response to the malaria parasite would be opportune targets for SIV infection." (PMID 19774084, 2009). "CCR5+ memory CD4+ T cells dramatically responded to parasitemias among the co-infected animals in a similar manner as the malaria-only animals." (PMID 19774084, 2009). "Persons with severe malaria were more likely to have a CD4 count <350/μL than were asymptomatic controls (OR 23.0, 95% CI 3.35–158.00, p<0.0001)." (PMID 19402961, 2009). "CD4+ T cells have been shown to play a central role in the development of protective immunity against blood stage malaria both in humans and rodent models." (PMID 19343215, 2009). "Similar findings have been reported in the case of a malaria vaccine candidate where an absolute requirement of CD4+ T-cells was observed to enhance passive immunity." (PMID 19340309, 2009). "CD4+CD25+ Treg block protective immunity in animal models of malaria 42 and filariasis 6, but are also required to minimise pathology caused by the response to pathogen invasion 43–45." (PMID 17563918, 2007). "CD4 T cell response to conserved regions of PfEMP-1 was significantly greater in malaria-exposed individuals than in unexposed Europeans, which suggests that these regions contain peptides recognized by T cells." (PMID 17026752, 2006). "Weaker effect of HIV-1 on malaria mortality (all groups): RR = 1.5 at CD4 >500/μL, RR = 2.0 at CD4 200–499/μL, and RR = 4.0 at CD4 <200/μL." (PMID 16229771, 2005). "Stronger effect of HIV-1 on malaria mortality (all groups): RR = 3.0 at CD4 >500/μL, RR = 6.0 at CD4 200–499/μL, RR = 12.0 at CD4 <200/μL." (PMID 16229771, 2005). "Weaker effect of HIV-1 on malaria incidence: RR = 1.0 at CD4 >500/μL, RR = 2.0 at CD4 200–499/μL, and RR = 4.0 at CD4 <200/μL." (PMID 16229771, 2005). "Stronger effect of HIV-1 on malaria incidence: RR = 1.5 at CD4 >500/μL, RR = 4.0 at CD4 200–499/μL, and RR = 8.0 at CD4 <200/μL." (PMID 16229771, 2005). "Malaria volunteers develop P. falciparum specific Abs and Th1 specific CD4+ and CD8+ T cells upon vaccination." (PMID 15579202, 2004). "While both of these surface marker-defined populations enrich for suppressive CD4+ T cells in different contexts, it is unclear whether these definitions can be used to identify malaria-specific Tr1 cells." (PMID 41000872, 2025). "Discovery of new genes that control CD4+ T cell responses may provide opportunities to improve immunity to malaria." (PMID 40132035, 2025). "Thus, while cMaf is critical for Tfh differentiation in experimental malaria, Myo1f and Prr13, although transcriptionally upregulated, are unnecessary for effector or memory CD4+ T cell responses." (PMID 40132035, 2025). "In this study we mined existing scRNA-seq datasets derived from Plasmodium-specific TCR transgenic and polyclonal CD4+ T cells during experimental malaria for novel genes that might control effector and memory differentiation." (PMID 40132035, 2025). "GLA-SE was selected based on its well-documented safety profile and its ability to enhance Th1-polarized CD4+ T-cell responses to co-administered antigens, particularly relevant as CD4+ T cells play a critical role in protective immunity against blood-stage malaria." (PMID 41210385, 2025). "In this study, we utilised existing scRNA-seq data from a mouse model of blood-stage malaria to hypothesise possible roles for Myo1f and Prr13 in CD4+ T cells." (PMID 40132035, 2025). "The CD4+ cell frequencies were similar between the two exposure groups; however, the frequency of proliferating Ki67+CD4 was higher among individuals with a first-time malaria." (PMID 40726977, 2025). "In addition, protection from clinical malaria following RTS,S vaccine administration was associated with the presence of polyfunctional CD4+ T cells." (PMID 39041038, 2024).
malaria (continued). "Similarly, memory resting CD4 T cells showed a drop in cell proportion during malaria from 19.09% at baseline to 13.85%, and then returned to 19.28% at recovery (p-value = 0.03)." (PMID 38992677, 2024). "This study describes a sequence of events arising from P2RX7 signaling in CD4+ T cells that respond to Plasmodium infection, which, together with the data published in this malaria experimental model, provides a clear view on the role of this signaling pathway in Th1 differentiation." (PMID 36993971, 2023). "Furthermore, continuous antigenic stimulation in chronic infection was suggested to enhance Th1 effector function and protective capacity of memory T cells in malaria in a model of TCR transgenic murine CD4+ T cells specific for MSP1." (PMID 37855243, 2023). "Thus, CD4+ TH cells are essential for effective protection against malaria, yet exactly how these subsets are related to each other during malaria infection, how they develop during acquisition of natural immunity and contribute to protection, is not clear." (PMID 38001069, 2023). "Our data suggest that even within this dramatically altered tissue environment, DCs are able to interact with both antigen and CD4+ T cells in a way that permits robust expansion of the latter, ruling out the existence of global DC dysfunction in the malaria-inflamed spleen." (PMID 36715223, 2023). "Given the importance of TF in orchestrating T cell fates, we focused on the ZEB2 TF and first confirmed that we could detect a population of ZEB2+ memory CD4+ T cells in PBMC from malaria-infected patients by flow cytometry." (PMID 38001069, 2023). "Pevonedistat had comparable effects in a malaria murine model, where deficiency of UBA3, which encodes the catalytic subunit of the NAE, significantly compromised survival, activation, and proliferation of CD4+ T cells and impaired TH1/TFH differentiation." (PMID 37031300, 2023). "In contrast, multigravid women had higher percentages of CD4+ T cells that produced TNFα in the absence of IFNγ, and these cells were associated with protection against malaria in pregnancy." (PMID 37634385, 2023). "In addition, proliferation is often required for lymphocyte differentiation and effector function, and the differentiation of Tfh and Th1 cells in malaria depends on a highly proliferative precursor CD4+ T cell subset." (PMID 37812650, 2023). "However, multiple lines of evidence have shown that malaria drives the expansion of regulatory CD4 T cells, particularly Type 1 regulatory (Tr1) cells that co-produce IFNγ and IL-10 in this disease." (PMID 37968278, 2023). "HIV infection was associated with lower CD4+ T-cells counts (mean cell count: 740±422 versus 1107±505; p=0.00001), both in malaria-infected and non-infected children (p=0.03 and p=0.000001)." (PMID 36600836, 2023). "Hence, these results indicate that CD4+ T cell STING promotes IL-10 production while suppressing IFN-γ production in a cell-intrinsic manner in vivo in experimental malaria." (PMID 37781920, 2023). "To further characterise the functional status of these malaria-specific CD4+ T cells, we performed an intracellular cytokine staining assay following a 24-h in vitro stimulation with iRBCs, PMA/Ionomycin, or media, using PBMCs from both the PROMOTE and DPSP cohorts." (PMID 37634385, 2023). "We also didn’t identify CD4+ T cell STING agonists active during malaria or their cellular source." (PMID 37781920, 2023). "Using more selective genetic tools to ablate antigen presentation specifically in DCs or B cells, we recently demonstrated that B cells, rather than DCs, are the dominant antigen-presenting cells (APCs) that direct activation and polarization of the CD4+ T cell response in mice with malaria." (PMID 36715223, 2023). "Future studies are also required to investigate whether Tr1/Th1 CD4 cells and Bregs induced in malaria responding in an antigen specific, or globally suppressive manner." (PMID 37968278, 2023).